EPCAM (epithelial cell adhesion molecule)
Diseases named in the same sentence as EPCAM in open-access papers (continued):
Sharing a sentence is not in itself a finding about the gene and the disease.
breast carcinoma (continued). "In this study, various breast cancer cell lines and endometrial cells were used to analyze different expression levels of multiple target antigens (EGFR, FOLR1, HER2, EpCAM, NG2, ANK3 and CTNNB1) through flow cytometry and fluorescence microscopy." (PMID 40422194, 2025). "Their research meticulously showcases the efficacy of EpCAM-targeted NIR-PIT in both human and murine breast cancer models, especially when combined with immune checkpoint inhibitors (ICIs)." (PMID 40964888, 2025). "In summary, this gene panel offers a reliable method for estimating the number of breast cancer cells mixed with bone marrow cells, with EGFR and EpCAM standing out as the most promising candidates due to their superior specificity and expression levels." (PMID 40073025, 2025). "In a previous study involving a small cohort of 48 stage I–II breast cancer patients, we found that CTC detection using an EpCAM-independent enrichment and DEPArray-based approach was statistically associated with vascular invasion." (PMID 40563997, 2025). "These internal structures are subsequently functionalized with anti-EpCAM antibodies to ensure the specific capture of EpCAM-positive human cancer cell lines, including MCF-7 breast cancer, SW480 colon cancer, and PC3 prostate cancer." (PMID 40277534, 2025). "Additionally, exosomal EpCAM expression is elevated in prostate cancer patients compared to that in healthy controls and has been identified as a biomarker in blood samples from pancreatic and breast cancer patients, where it also serves as a therapeutic target." (PMID 39996844, 2025). "Based on the CellSearch analyses, PLXNB2high breast cancer correlated with detectable blood CTCs, stained as cytokeratin (CK)+DAPI+CD45− cells after enrichment via anti-EpCAM magnetic beads." (PMID 40818975, 2025). "It successfully identified breastcancer biomarkers, namely EpCAM+ EVs and GPC-1+ EVs, from breast cancer cells." (PMID 40720603, 2025). "Gene expression correlation analysis revealed that USP30 negatively correlates with the expression of stem cell markers such as MMP2, MMP9, MYC, OCT4(POU5F1), NANOG, ALDH1A3, CD133 (PROM1), EPCAM, CD24, and ITGA6 in breast cancer cohorts." (PMID 41306556, 2025). "EpCAM c.344T>C may weaken protein folding, thereby promoting cervical cancer progression, enhance tumor cell stemness to facilitate breast cancer growth, and impair EpCAM’s inhibitory effect on cathepsin L, increasing the invasiveness of non-small cell lung cancer." (PMID 41164816, 2025). "The upregulated differentially expressed breast cancer stem cell markers included CD56/NCAM1, POU5F1, PROCR/CD201, ITGA6, and the downregulated were ESR1, PGR, HER2/ERBB2, ABCG2, CD44, CD24, EPCAM, and CDH1." (PMID 40690373, 2025). "By capturing darkfield images and performing analysis using in-house machine learning pipeline, a successful diagnosis and differentiation of HER2-positive breast cancer at Stages II, III, and IV was established based on CD24 and EpCAM expression levels." (PMID 41404198, 2025). "Breast cancer CTCs are classically defined as CD45–, EpCAM+, and Cytokeratin 8/18/19+ (classical CTCs or cCTCs), and this definition has yielded important insights into how CTC shedding predicts survivorship." (PMID 40867346, 2025). "EPCAM and KRT18 were employed to label epithelial cells, whereas ALDH2, CD55, and ALDH6A1 were used to identify breast cancer stem cells." (PMID 40092692, 2025). "Their aim was to capture two different human breast cancer cell lines (MCF-7 ~ 15–17 μm and MDA-MB-231 ~ 12 μm) from blood cells through specific conjunction of Epithelial Cell Adhesion Molecule (EpCAM) to magnetic nanoparticles." (PMID 39337795, 2024). "Statistical analysis showed that both EpCAM and CD24 markers can detect HER2-positive breast cancer at Stages II, III, or IV." (PMID 39513819, 2024).
breast carcinoma (continued). "used biotinylated SERS nanotags to capture breast cancer CTCs on streptavidin coated micro-posts for a 5-plex SERS biosensing of MUC1, EpCAM, EGFR, HER2, and CD133." (PMID 38811455, 2024). "EpCAM overexpression was shown to promote the expression of stem cell markers (NANOG, SOX2, and OCT4) in breast cancer cell lines." (PMID 39456890, 2024). "In contrast, breast cancer (SKBR3) cell has an average size of 12.5±2.1μm and ~600,000 surface EpCAM antigens per cell." (PMID 39229148, 2024). "Our research outcomes encompass successful multiplexed immunolabelling of Her2, CD44, and EpCAM in the SK-BR-3 and MDA-MB-231 breast cancer cell lines." (PMID 39170968, 2024). "Quantum dots were also applied for breast cancer cell detection, utilizing a trio of antibodies: anti-HER2/neu for capturing cells on silanized glass, anti-EpCAM for labeling, and a third antibody against anti-EpCAM conjugated to QDs for imaging." (PMID 38730959, 2024). "Using the machine learning-based imaging analysis and the DISVT, we quantified EVs that are positive for EpCAM or CD24 and examined their ability to detect HER2-positive breast cancer at different stages." (PMID 39513819, 2024). "In contrast, a significant increase in the expression levels of human CD24, as well as the epithelial genes such as E‐Cadherin, EpCAM, and Mucin, was observed in tumor tissues of mice xenotransplanted with CD24+‐breast cancer cells." (PMID 38522013, 2024). "In one additional murine cell line (MMTV-NIC, also derived from an FVB/n mammary tumor) and the human MDA-MB-468s, epithelial cells (EpCAM+) expressed B7-H4." (PMID 38687247, 2024). "This dataset, comprised of ER-positive, PR-positive, HER2-positive and TNBC, showed a distinct clustering, with multiple EPCAM+ and Keratin-8+ (KRT8) clusters corresponding to the heterogeneous tumor cell populations in each of the breast cancer subtypes." (PMID 36635273, 2023). "In a recent study, using RT-qPCR, two panels of transcripts related to the presence of CTCs (Panel 1: CK19, EpCAM, SCGB2A2 and Panel 2: EMP2, SLC6A8, HJURP, MAL2, PPIC and CCNE2), in two cohorts of breast cancer patients (metastatic and early), were evaluated." (PMID 37046848, 2023). "The markers SCGB2A2, EpCAM, SLC6A8 and PPIC were detectable in about half of the metastatic breast cancer samples." (PMID 36831613, 2023). "By analyzing plasma samples from healthy donors and breast cancer patients, we identified epidermal growth factor receptor 2 (HER2) and epithelial cellular adhesion molecule (EpCAM) as exosomal biomarkers for detecting HER2-positive breast cancer." (PMID 36770486, 2023). "SIX1 showed a significant positive correlation with breast cancer stem cell markers such as ALDH1A1, EPCAM, ITGB1, and SOX2." (PMID 38031089, 2023). "In an independent study, sera-derived exosomes from breast cancer patients were used to characterize CD24 and EpCAM as markers for exosomes." (PMID 37629204, 2023). "The six-gene panel was superior to the commonly used marker genes for epithelial breast cancer CTCs, EpCAM and human mammaglobin A (SCGB2A2), both in samples from patients with early and advanced breast cancer." (PMID 36831613, 2023). "The tumor-specific marker genes (i.e. EPCAM, KRT8, EPCAM, B2M, FCA1 and KRT19) were also highly expressed in the tumor regions of prostate, colorectal, liver cancer, pancreas and breast cancer." (PMID 36243975, 2023). "In this study, a modified AAV2 viral vector was used, in which EpCAM-specific DARPin EC1 was fused to the VP2 protein of AAV2, creating a viral vector that can target breast cancer cells." (PMID 38082377, 2023). "To achieve this, we first select two different (commonly used) breast cancer cell lines, being SK-BR-3 and MCF7, with the aim to have model systems for two breast cancer biomarkers, i.e., HER2 and EpCAM, respectively." (PMID 36835174, 2023).
breast carcinoma (continued). "Other CAR‐T cell targets under investigation in the clinical trial for relapsed or refractory breast cancer include NKG2D ligands and EpCAM." (PMID 35762299, 2022). "Downregulation of the Wnt signaling pathway, cancer stem cell markers oct4, Notch1, EpCAM, and CD44 was a common mechanism encountered in many tested breast cancer cell lines with eugenol." (PMID 36362950, 2022). "As a proof of concept and to validate our isolation technology, we use immune recognition to specifically isolate cells expressing two specific antigens—EpCAM and EGFR —which have been thoroughly studied as biomarkers for the targeting of breast cancer cells." (PMID 36004905, 2022). "Clinical trials are underway to assess the effects of CAR-T cell therapy for treating breast cancer, including CAR-T cells recognizing epithelial cell adhesion molecule (EpCAM) (NCT02915445), cleaved MUC1 (NCT04020575, NCT02792114), and ROR1 (NCT05274451)." (PMID 36387071, 2022). "The breast cancer cell MCF-7 was captured and enriched by anti-epithelial cell adhesion molecule (EpCAM) antibody-modified magnetic nanospheres." (PMID 36354462, 2022). "Survival was estimated to be worse in patients with higher expression EpCAM in breast cancer tissue, especially in the luminal B HER2 positive and basal-like breast cancer, and ovarian, prostate, and gall bladder cancers." (PMID 35208477, 2022). "Downregulation of cytokeratin 18 increased EpCAM expression by activating Wnt/β-catenin, leading to partial EMT and elevated stemness of breast cancer cells." (PMID 36369033, 2022). "In patients with operable or locally advanced breast cancer, CTC positivity is reported in 5–29% of cases when using EpCAM-based enrichment or direct immunostaining of cytological blood samples to detect epithelial markers." (PMID 36428760, 2022). "To assess the phenotypic impact of LATS1 in human breast cancer cells, we subjected MDA-MB-468 cells to FACS analysis, employing EpCAM as a luminal marker." (PMID 36443319, 2022). "Targets under examination include epithelial cell adhesion molecule (EpCAM) in non-small cell lung carcinoma, glycan 3 (GPC3) in live cancer, HER2 in breast cancer, and prostate-specific membrane antigen (PSMA) in prostate cancer." (PMID 35745815, 2022). "In the cell experiment, they used three kinds of breast cancer cells (BT-474: HER2, EpCAM expressed; MCF-7: HER2-negative, EpCAM-positive: UACC-812: HER2-positive, EpCAM-negative), and a normal breast epithelial cell (MCF-10: HER2, EpCAM-negative)." (PMID 36235208, 2022). "EpCAM, as well as the cancer-related protein CD24, has been detected on EVs isolated from ascites and pleural effusions from breast cancer patients." (PMID 35012489, 2022). "Breast cancers have been efficiently treated by CAR-NK therapy targeting a variety of antigens highly expressed on the surface of breast cancer cells, including HER-2, tissue factor, and EpCAM." (PMID 36612114, 2022). "We used the human breast carcinoma cell line BT-474 and the human lung carcinoma cell line Calu-3 as model cancer cell lines, which both overexpress HER2 and EpCAM." (PMID 34070171, 2021). "HDAC inhibitors reversed EMT by inhibiting Epithelial Cell Adhesion Molecule (EpCAM) cleavage and WNT signaling in breast cancer cells." (PMID 33445642, 2021). "As an example, ESA+/CD44+/CD24−, and ALDH1+ were detected in breast cancer stem cells (BCSCs); CD133+ in colon, glioblasoma, gastric and lung; EpCAM, CD133/EpCAM, CD90+ ESA+CD133+ CD44+CD24+ in liver; and ESA+/CD44+/CD24+ in pancreatic CSCs." (PMID 34051847, 2021). "EpCAM+, CD44+, CD24- CSCs were 10-fold more likely to induce tumors compared to EpCAM-, CD44+, CD24- CSCs in breast cancer." (PMID 33889547, 2021). "EpCAM overexpression promoted EMT and expression of stem cell markers (NANOG, SOX2, and OCT4) under hypoxic conditions in breast cancer cell lines and this effect also occurred through NF-κβ signaling as well." (PMID 34209658, 2021).
breast carcinoma (continued). "For example, the FDA approved the Cell Search enrichment method for CTC detection in breast cancer and prostate cancer patients using EpCAM and CD45 antibodies to capture EpCAM + cells from the blood." (PMID 34412644, 2021). "Various αTAA–αCD3 and αTAA–αCD28 BiMAb in a tetravalent IgG1-Fc based format have been analyzed, targeting multiple breast cancer antigens including HER2, EGFR, CEA, and EpCAM." (PMID 34484225, 2021). "Depending on the expression of EpCAM, CK7, Snail, N-cadherin, and Vimentin, we considered the probability of 24 CTC phenotypes in breast cancer patients." (PMID 33801519, 2021). "Studies have found that BRIP1 can promote the invasion of breast cancer (BC) cells by regulating the expression of multiple downstream target genes, such as MGAT5, EPCAM, and CXCL12, especially in the triple-negative phenotype MDA-MB-231 cell line." (PMID 34408776, 2021). "Genes related to proliferation (MKI67, CCNA2), differentiation (EPCAM, CDH1), epithelial to mesenchymal transition (VIM, SNAI2), pluripotency and breast cancer stem cells (SOX2, NANOG, CD44) were included." (PMID 34090457, 2021). "Applying 2D Ti3C2 MXenes nanosheets and anti-EpCAM as the ECL probe and the capture aptamer, Zhang designed a reliable, sensitive biosensor to detect breast cancer in serum samples with a detection limit of 125 particles/μL." (PMID 34940275, 2021). "An in vivo study also showed that ZMYND8 overexpression significantly reduces the subcutaneous 4T1 murine breast cancer growth and increases the expression of differentiation-related genes, including CK5, CK18, CK19, and EPCAM in Balb/c mice." (PMID 33670804, 2021). "We first tested the two antibodies against the human breast carcinoma positive control cell lines, MCF-7 and MDA-MDA-231, as both cell lines should express EpCAM, with MCF-7 being the higher expressing cell line." (PMID 33614766, 2021). "EpCAM-positive exosomes from MCF7 and M231 cell culture medium were significantly higher than those from NF culture medium, and this was also observed in breast cancer patients (n = 6) compared to healthy controls (n = 3) (p < 0.01)." (PMID 34073560, 2021). "TGF-β1 treatment induced EMT and migration in breast cancer cell line MCF-7, and this was shown to be modulated through a JNK/AP-1/EpCAM signaling axis." (PMID 34209658, 2021). "Studies have identified CD44+CD24− in breast cancer; CD44+CD24+EpCAM+ in pancreatic or ovarian cancer; and a high expression of neuron stem markers, such as CD133, CD44, and Nestin, and transcript factors, such as SOX2 and OCT4, in GBM." (PMID 34069945, 2021). "We expressed WT, or C66Y EpCAM, in the human WHIM-3 breast and murine PyMT BO-1 mammary cancer cell lines." (PMID 33980181, 2021). "The immunoblot analysis of the 6 mammary tumors that express oncogenic KRAS from its endogenous locus showed that the basal-like cancers (tumors 4 to 6) express EpCAM, E-cadherin, and CK14 but lack expression of N-cadherin and CK8." (PMID 34145248, 2021). "Several established markers of breast cancer CSCs, including CD44+/CD24−/low phenotype and CD133, ALDH1, EpCAM, and nestin overexpression, have been correlated with poorer prognosis diagnosed patients." (PMID 33375383, 2020). "In order to further evaluate in vivo the impact of P2Et in BCSC-enriched breast cancer models (triple negative and luminal), we analyzed the expression of CD44, CD24, EpCAM, CD49f and ALDH in human cell lines." (PMID 33184339, 2020). "Based on this data, the expression of BCSC markers (CD44, CD49f, P-cadherin, EpCAM, and ALDH1) was determined and found to be significantly enriched in breast cancer brain metastases when compared to primary tumors." (PMID 33182375, 2020). "By forming a RNA-protein complex with TEAD and down-regulating EpCAM, ITGB4 and VEGF expression, MALAT1 suppresses colorectal and breast cancer cell migration, invasion, and metastasis." (PMID 32174966, 2020).
breast carcinoma (continued). "In accordance, we also found a significant enrichment of the BCSC markers CD44, CD49f, P-cadherin, EpCAM, and ALDH1 in human breast cancer brain metastasis when compared with unmatched primary tumors previously analyzed by our group." (PMID 33182375, 2020). "Mammary stem cell markers or combined markers have been certified in different stages of stem cells in breast cancer, including ALDH, CD44, CD24, ITGA6/EpCAM, and PROCR." (PMID 31340763, 2019). "In a medium cohort of patients in previous studies, these findings revealed that ALDH1A3, PROCR, ITGA6+, ITGA6+/EpCAM− and ITGA6−/EpCAM+ were correlated with reduced RFS or overall survival of these breast cancer patients." (PMID 31340763, 2019). "Another way for EpCAM to promote invasion of breast cancer cells (ER negative) would be via upregulation of IL8 expression (a member of the CXC chemokine family associated with increased breast cancer invasion in vitro) but a precise molecular mechanism has not been identified yet." (PMID 31225512, 2019). "Anti-EpCAM CAR engineered NK-92 displayed high and selective cell-killing activity against EpCAM-expressing breast carcinoma cells that were resistant to the natural cytotoxicity of unmodified NK cells." (PMID 30805309, 2019). "EMP-specific cellular phenotypes can be isolated using EpCAM, Integrin-β4 or CD44/CD24 expression in basal-like cell lines representing TNBC, or by using E-cadherin in mammary carcinoma in mouse PyMT models." (PMID 31234417, 2019). "Assessment of the expression of other BCSC markers -ALDH1A1, EpCAM, CXCR4, and CD133 in stable NRF1 overexpressing CD44+CD24− and CD44+CD24+ subpopulations showed as many as 10 different downstream breast cancer progenitor cell subpopulations." (PMID 30486409, 2018). "The combined NRF1 overexpression and treatment with E2 also led to reprogramming of CD24+ and CD24−CD44− subpopulations with multiple breast cancer stem cell signatures containing ALDH1A1, EpCAM, CXCR4, or CD133." (PMID 30486409, 2018). "EpCAM is a preferred biomarker for CTC detection, since this protein is frequently expressed in prognosis-relevant CTC, e.g. in breast cancer." (PMID 29163804, 2017). "It is also interesting to note that in most early breast cancer patients that relapsed early, SOX17 gene promoter was found highly methylated in the primary tumour, in the EpCAM-positive CTC-fraction and in ctDNA." (PMID 29069768, 2017). "Two breast cancer cell lines, Hs578T and SKBR3, representing FAPα + CTCs (CTCFAPα) and EpCAM + CTCs (CTCEpCAM), respectively, were chosen to evaluate cell recovery and cross-reactivity using the dual selection strategy." (PMID 29657983, 2017). "In this study, the distribution of two membrane proteins, EpCAM and epidermal growth factor receptor (EGFR), was observed in two types of living breast cancer cell lines, Michigan Cancer Foundation-7 (MCF-7) and MDA-MB-231." (PMID 29257118, 2017). "In early breast cancer, SOX17 methylation status in the EpCAM-positive CTC-fraction was found to be correlated with CK-19 mRNA expression (P = 0.006)." (PMID 29069768, 2017). "To investigate EpCAM expression heterogeneity in circulating tumor cells, we designed a model system for EMT-induced breast cancer cells." (PMID 27013581, 2016). "For example, the CSC surface markers CD44+ and CD24− were defined in breast cancer, CD20+ and ABCB5+ in melanoma, and EpCAM+, CD44+, and CD166+ in colon cancer." (PMID 27172898, 2016). "The present study investigated the tumorigenic potential of circulating EpCAM+ and CD90+ cells isolated from mobilized leukapheresis products from three breast cancer patients collected for autologous hematopoietic stem cell transplantation." (PMID 28721373, 2016). "Most recently, EpCAM, CD44 and MET have also been identified in circulating tumor cells (CTCs) of breast cancer patients exhibiting metastasis." (PMID 26243458, 2016).